CTNNB1 (catenin beta 1)
Diseases named in the same sentence as CTNNB1 in open-access papers (continued):
Sharing a sentence is not in itself a finding about the gene and the disease.
ameloblastoma (8 papers, 2017 to 2025). The most common odontogenic tumor, arising from the epithelial component of the embryonic tooth and usually affecting the molar-ramus region of the mandible or maxilla. "We recently reported that 10 out of 11 patients with calcifying cystic odontogenic tumors (calcifying odontogenic cyst) have mutations in the CTNNB1 gene, while 12 out of 14 patients with ameloblastoma have mutations in the BRAF gene." (PMID 32113465, 2020). "Ameloblastoma cases with CTNNB1 mutations (cases #19 and #20) also accumulated nuclear beta-catenin." (PMID 28658279, 2017). "Aside from the SMO mutations, APC mutations have been detected in 3/6 ameloblastomas, and CTNNB1, PIK3CA, SMARCB1, PTEN, CDKN2A mutations have been reported in a few cases and tend to occur in a non-mutually exclusive manner with BRAF p.V600E mutation and with each other." (PMID 35048058, 2021). "It is notable that the presence of two or three gene mutations, including somatic mutations in KRAS, PIK3CA, PTEN, FGFR, CDKN2A, and CTNNB1 in the background of either BRAF or SMO mutation-positive ameloblastomas, exclusively occurred in solid/conventional tumors." (PMID 35048058, 2021). "Inactivating APC mutation and CTNNB1 activating mutation leads to strong and aberrant cellular β-catenin accumulation, and such phenomena have been observed in some odontogenic epithelial tumors, including ameloblastoma and odontogenic carcinoma." (PMID 35048058, 2021). "However, somatic KRAS, PIK3CA, PTEN, FGFR, CDKN2A, and CTNNB1 co-occurred also in the background of either BRAF- or SMO-mutated ameloblastomas." (PMID 29388014, 2018). "In a similar way, other somatic mutations have been reported in ameloblastoma, mainly affecting: SMO, other MAPK pathway-related genes such as KRAS, NRAS, HRAS, FGFR2 and in a lower frequency, PTEN and CTNNB1 among others." (PMID 35048068, 2021). "Thus, we closely examined cases of ameloblastoma with both BRAF and CTNNB1 mutations (cases #19 and #20)." (PMID 28658279, 2017). "Notably, CTNNB1 Ser37Cys and CTNNB1 Gly34Glu were found in addition to BRAF Val600Glu in ameloblastoma cases #19 and #20, respectively." (PMID 28658279, 2017). "Nevertheless, some cases of odontogenic tumors genetically overlap, such as ameloblastoma cases #19 and #20, in which BRAF and CTNNB1 are present." (PMID 28658279, 2017).
breast tumor (8 papers, 2012 to 2022). "With regard to activation of the canonical Wnt pathway, we observed that RSPO3‐driven breast tumors expressed the Wnt/β‐catenin target genes Axin2, Wif1, Znrf3, and Ctnnb1 itself, however at significantly lower levels than their WNT1‐driven counterparts." (PMID 36106661, 2022). "The up-regulated genes include CTNNB1, GSC and TWIST1, encoding for transcription factors known to be activated during breast tumor metastasis, and AHNAK and AKT1, variously involved in tumorigenesis and cell motility." (PMID 24962430, 2014).
Cirrhosis (8 papers, 2012 to 2021). A chronic disorder of the liver in which liver tissue becomes scarred and is partially replaced by regenerative nodules and fibrotic tissue resulting in loss of liver function. "Next, we determined the accuracy of CTNNB1 32–37 qPCR assay by detecting mutations in liver tissue DNA from patients with hepatitis (n = 35), cirrhosis (n = 35), or HCC (n = 73) and validating by Sanger sequencing." (PMID 34441409, 2021). "ROC curve analysis of these biomarkers showed promising diagnostic value but CTNNB1, SERPIND1 and SPINK1, with AUC as 0.94, 0.88 and 0.89, respectively, demonstrated that they have highest diagnostic ability to detect early stage HCC developing on the background of cirrhosis." (PMID 34469466, 2021). "Finally, we believe that viral insertions and structural rearrangements activating CCNA2 or CCNE1 are early events triggering hepatocarcinogenesis because they occur in patients without cirrhosis and in absence of other oncogenic event like CTNNB1 mutations." (PMID 30531861, 2018). "Since liver-biopsies may not be feasible in many HCC patients due to cirrhosis that usually co-exists, immunohiostochemistry for assessment of β-catenin and/or GS localization as an indicator of CTNNB1 mutations is often not possible." (PMID 24892551, 2014). "RhoA, CTNNB1 and SPINK1 showed a significant 3.3-, 3.2- and 3.18-folds upregulation, respectively, in HCC patients compared to cirrhosis patients while IFITM3 and SERPIND1 presented a 2.24-fold change." (PMID 34469466, 2021). "Our suggested mRNA signature including CTNNB1, RhoA, SPINK1, IFITM3 and SERPIND1, alongside other platelets mRNA, can be utilized as biomarkers for comparison of hepatic cirrhosis and HCC." (PMID 34469466, 2021). "A combination of CTNNB1, SERPIND1 and SPINK1 would generate an AUC of 1 which would be the ideal scenario for early-stage HCC detection when developing from cirrhosis." (PMID 34469466, 2021). "Genes involved in cirrhosis development (ABCG2, CTNNB1, B2M, IFNAR1, IFNAR2), and hepatic cholestasis (CYP7B1) were found significantly down-regulated in patients without HCC." (PMID 22792259, 2012). "Thus, in order to analyze the involvement of this pathway in progression of cirrhosis to HCC, we assessed the transcriptomic expression of CTNNB1 in both study groups." (PMID 34469466, 2021). "On the other hand, patients who did not harbor CTNNB1 mutations showed significantly higher LECT2 level (54.26±22.25 ng/mL; n = 46) than those with cirrhosis and from healthy volunteers (p = 0.0044 and 0.0176, respectively)." (PMID 24892551, 2014).
Cognitive impairment (8 papers, 2017 to 2025). Abnormal cognition is characterized by deficits in thinking, reasoning, or remembering. "Loss-of-function mutations in the CTNNB1 gene cause β-catenin deficiency, resulting in CTNNB1 syndrome, a rare neurodevelopmental disorder characterized by motor and cognitive impairments." (PMID 40896583, 2025). "This suggests that CTNNB1 is an important target gene of AO in the treatment of cognitive impairment in kidney deficiency." (PMID 36533181, 2022). "Variants and genotype-phenotype correlations of 404 patients with CTNNB1 neurodevelopmental disorder suggest that the most common clinical feature in patients with pathogenic or likely pathogenic variants of the CTNNB1 gene is a mild-to-profound cognitive impairment." (PMID 38225558, 2024). "CTNNB1 neurodevelopmental disorder is characterized in all individuals by mild-to-profound cognitive impairment." (PMID 39967850, 2025). "CTNNB1 neurodevelopmental disorder with spastic diplegia and visual defects (OMIM 615,075, also known as NEDSDV or CTNNB1-NDD) is hallmarked by two main symptoms: cognitive impairment and exudative vitreoretinopathy." (PMID 38225558, 2024). "Disease-causing variants in CTNNB1 may lead to the development of exudative vitreoretinopathy type 7, of which the clinical symptoms do not include any cognitive impairment or neurological abnormalities." (PMID 38225558, 2024).
colorectal adenoma (8 papers, 2010 to 2021). An adenoma that arises from the colon or rectum. "On the other hand, several molecular studies on sporadic colorectal adenomas have revealed CTNNB1 mutations preferentially at codons 41 and 45 at a significantly higher frequency than in CRC." (PMID 33115416, 2020). "Reports of homozygous CTNNB1 mutations are found for parathyroid adenoma and for two colorectal adenomas." (PMID 33115416, 2020). "The reason for the selection of codon 41 or 45 mutations in MSI-H cancers is as unclear as the timing of CTNNB1 first and second hit mutations in the colorectal adenoma to carcinoma sequence." (PMID 33115416, 2020). "A relation between the presence of the BRAFV600E mutation, change in CTNNB1 expression, and consequent activation of the Wnt signaling pathway has been shown in sessile serrated colorectal adenomas and sessile serrated adenomas dysplasia, as well as in skin melanoma." (PMID 26625260, 2015). "Our results showed that APC, CTNNB1, IGF1, and KLF5 were frequently mutated in normal-colorectal adenoma." (PMID 31336886, 2019). "We identified genes with somatic mutations in the normal-colorectal adenoma samples, APC, CTNNB1, LRP5, FBXW7, and ATM, which overlapped with the TCGA data." (PMID 31336886, 2019). "Mutations in CTNNB1 (β-catenin) have been reported as an alternative to APC mutations and were found more frequently in small colorectal adenomas." (PMID 22848674, 2012).
CTNNB1 syndrome (8 papers, 2022 to 2025). "CTNNB1 syndrome, a rare autosomal dominant neurodevelopmental disorder, is caused by pathogenic loss-of-function (LoF) variants in the Ctnnb1 gene, which encodes the β-catenin protein, a critical regulator of the Wnt/β-catenin signaling pathway." (PMID 39833474, 2025). "CTNNB1 syndrome is a neurodevelopmental disorder caused by a variety of de novo mutations that result in heterozygous loss-of-function alleles in the CTNNB1 gene." (PMID 39949392, 2025). "CTNNB1 syndrome is a rare neurodevelopmental disorder caused by a likely pathogenic or pathogenic variant in the CTNNB1 gene." (PMID 39976812, 2025). "The CTNNB1 syndrome is a recently described autosomal dominant neurodevelopmental disorder caused by de novo LoF variants in the CTNNB1 gene." (PMID 37895192, 2023). "CTNNB1 Syndrome is a severe autosomal dominant neurodevelopmental disorder usually caused by de novo loss-of-function mutations in the CTNNB1 (Cadherin-associated protein, beta 1) gene." (PMID 36293418, 2022). "Furthermore, targeting intron 2 would allow replacement of most of the coding region of the CTNNB1 transcript, making this approach widely applicable to CTNNB1 syndrome-associated mutations, which are spread across the entire gene." (PMID 40896583, 2025). "In addition, the availability of patient-derived cell models and mouse models of a CTNNB1 loss-of-function model has opened exciting avenues for collaboration and research in the field of CTNNB1 syndrome." (PMID 39949392, 2025). "In this study, we aimed to optimize 3′ trans-splicing for the CTNNB1 gene that could correct most reported mutations that cause CTNNB1 syndrome while maintaining the endogenous transcriptional regulation." (PMID 40896583, 2025). "While gain-of-function (GoF) mutations in Ctnnb1 are linked to cancers such as liver and colorectal cancer, autosomal de novo loss-of-function mutations can lead to CTNNB1 syndrome, a neurodevelopmental disorder (NDD; Phenotype MIM Number 615075)." (PMID 39833474, 2025). "Following the initial discoveries of gain-of-function mutations in Ctnnb1 linked to oncogenesis, numerous de novo mutations have been identified and linked to CTNNB1 syndrome, a severe neurodevelopmental disorder." (PMID 39833474, 2025). "The present paper provides a comprehensive and up-to-date review of published cases of CTNNB1 Syndrome, an analysis of the prevalence of the most common symptoms, and a classification of CTNNB1-associated mutations according to the severity of their respective phenotypes (Supplement A)." (PMID 36293418, 2022). "CTNNB1 syndrome is a rare neurodevelopmental disorder that affects the development and maturation of the brain due to changes in the CTNNB1 gene." (PMID 39949392, 2025). "Testing treatments on CTNNB1 patient cells plays a crucial role in assessing the efficacy of therapeutic interventions, a fundamental step in the development of precise treatments for CTNNB1 syndrome." (PMID 39949392, 2025). "This includes the development and characterization of cellular and animal models of CTNNB1 syndrome and the advancement of various programs to develop treatments for CTNNB1, including small molecule treatment, RNA-based therapy, AAV9 gene replacement therapy (GRT), and DNA modification techniques." (PMID 39949392, 2025).
cyst (8 papers, 2017 to 2025). A sac-like closed membranous structure that may be empty or contain fluid or amorphous material. "Histologically, clusters of catenin-rich cells have been identified in the tumor–brain border and the tumor’s cyst wall, suggesting a possible role of CTNNB1 mutations in the aggressive expansion of some adamantinomatous CPs." (PMID 37174978, 2023). "In the present study, sequencing showed that the mutations of CTNNB1 in the cyst wall were identical to those in the solid body, further indicating that the cyst wall contains tumor cells that are transformed through the same mechanism, and so it was a component of the tumor." (PMID 36810626, 2023). "The level of CTNNB1 transcription was quantified in 6 cases of cyst wall with a sufficient amount of RNA and 4 cases of solid tumor component in comparison with 4 cases of normal brain tissue." (PMID 36810626, 2023). "This further suggests that the increase of CTNNB1 transcription is also an important mechanism of tumorigenesis involving cells in both the cyst wall and the solid tumor." (PMID 36810626, 2023). "Reducing β-catenin hyperactivation in KCTD1 mutants through heterozygosity for the β-catenin gene Ctnnb1 attenuated mTOR hyperactivation and partially rescued the renal fibrosis and cyst formation phenotype in these mice." (PMID 35468900, 2022). "In case 10, however, neither the cyst wall nor the matched solid tumor component had CTNNB1 mutation." (PMID 36810626, 2023). "The results of PCR suggested that the transcription of CTNNB1 gene in the cyst wall is higher than that in normal brain tissue and is not significantly different from that of the rest of the tumor." (PMID 36810626, 2023).
diabetes (8 papers, 2016 to 2026). "AXIN1 is down regulated in diabetes condition and CTNNB1 activation is associated with an increment in glucose uptake." (PMID 27490120, 2016). "However, correlations were found between − 146 bp TERTp mutation and concentration of alfa-fetoprotein (p = 0.004), and between CTNNB1 mutations and diabetes mellitus (p = 0.004) and extent of encapsulation (p = 0.03)." (PMID 35962322, 2022). "In a diabetes mouse model, CTNNB1 and DLK1 levels were further assessed using ELISA, Western blot, qRT-PCR, and immunohistochemistry." (PMID 41961207, 2026). "In this study, through bioinformatics analysis, we screened seven DCRGs, including PPARG, MMP9, CTNNB1, TNF, TGFB1, PTGS2, and HIF1A, and established a DCIN to comprehensively understand the diabetes-inflammation-cancer interaction." (PMID 37033970, 2023). "Our results uncovered that AS-IV can protect retinal cells against diabetes induced retinopathy, which may act on target proteins AKT1, CASP3 and HIF1α, VEGFA, IL6, IL1β, SRC and CTNNB1, and might be involved in the regulation of PI3K-AKT signaling pathway." (PMID 35814228, 2022).
exudative vitreoretinopathy (8 papers, 2018 to 2024). Familial exudative vitreoretinopathy (FEVR) is a rare hereditary vitreoretinal disorder characterized by abnormal or incomplete vascularization of the peripheral retina leading to variable clinical manifestations ranging from no effects to minor anomalies, or even retinal detachment with blindness. "While somatic gain-of-function mutations in the CTNNB1 gene cause diverse malignancies, germline loss-of-function mutations cause neurodevelopmental disorders or familial exudative vitreoretinopathy." (PMID 37416820, 2023). "Recently, germline loss-of-function pathogenic variants in CTNNB1 have been reported to cause neurodevelopmental disorders with spastic diplegia and visual defects (NEDSDV, MIM# 615075), and familial exudative vitreoretinopathy (MIM# 617572)." (PMID 37416820, 2023). "A recent survey of the literature found that approximately 50% of such CTNNB1 mutations are associated with ophthalmic abnormalities including familial exudative vitreoretinopathy spectrum (FEVR), visual field defects, retinal detachment, strabismus, hyperopia, and lens and vitreous opacities." (PMID 35246174, 2022). "Various visual defects (including familial exudative vitreoretinopathy, retina detachment and myopia etc.)have also been reported in recent WES studies of people with mutations in CTNNB1." (PMID 30245926, 2018).
hepatitis C (8 papers, 2014 to 2024). "Females were more often CTNNB1 mutation positive (20.1% vs. 5.6%, P = 0.028) and there was a trend towards an association with Hepatitis C virus infection etiology in plasma mutation positive patients (P = 0.071)." (PMID 33827453, 2021). "CTNNB1 mutations are reported to be associated with hepatitis C infections." (PMID 27252594, 2016). "β-catenin expression is a key component in the molecular classification of HCC; activating mutations of its gene CTNNB1 define a clear subset of HCC patients and typically associated with hepatitis C or alcohol-related liver disease." (PMID 33335270, 2020).